TLX3 (T cell leukemia homeobox 3)
Synonyms: HOX11L2; RNX
Tractability: PROTAC: ubiquitination databases record sites on it.
Gene: Protein-coding gene on chromosome 5 (171,309,248 to 171,312,139, forward strand). Ensembl gene ENSG00000164438.
Subcellular location: Nucleus
Subcellular location (Human Protein Atlas): Nucleoplasm
Gene Ontology:
Molecular function: protein binding; sequence-specific double-stranded DNA binding; DNA-binding transcription factor activity, RNA polymerase II-specific; DNA binding; DNA-binding transcription factor activity
Biological process: animal organ development; regulation of transcription by RNA polymerase II; regulation of DNA-templated transcription
Cellular component: nucleoplasm; chromatin; nucleus
Genetic constraint (gnomAD): Loss-of-function variants: 11 observed, 18.14 expected, observed/expected ratio (o/e) 0.61, 90% interval 0.38 to 1. The synonymous counts are far from expectation, so gnomAD's model fits this gene poorly and the ratio says little. Missense variants: 375 observed, 377.44 expected, observed/expected ratio (o/e) 0.99, 90% interval 0.91 to 1.08. Synonymous variants: 221 observed, 172.95 expected, observed/expected ratio (o/e) 1.28, 90% interval 1.14 to 1.43.
Homologues: Orthologues: macaque TLX3 (100% identical), rabbit TLX3 (100% identical), dog TLX3 (99% identical), guinea pig TLX3 (99% identical), mouse Tlx3 (99% identical), pig TLX3 (99% identical), rat Tlx3 (99% identical), chimpanzee TLX3 (99% identical), tropical clawed frog tlx3 (81% identical), zebrafish tlx3b (70% identical), zebrafish TLX3 (57% identical). Paralogues in human: TLX1 (64% identical), TLX2 (58% identical), HOXB2 (23% identical), HOXA2 (22% identical), HOXB3 (21% identical), HOXA3 (20% identical), HOXD1 (20% identical), HOXD3 (20% identical), HOXA1 (19% identical), HOXB4 (19% identical), HOXA4 (18% identical), HOXC11 (18% identical), and 30 more.
Diseases named in the same sentence as TLX3 in open-access papers:
TLX3 is named in the same sentence as 23 diseases in open-access papers, as found by Europe PMC text mining. Sharing a sentence is not in itself a finding about the gene and the disease. The quoted sentences say what the papers report.
T-cell acute lymphoblastic leukemia (12 papers, 2009 to 2024). Acute lymphoblastic leukemia of T-cell origin. "For example, we confirmed that the transcription factors TLX1 and TLX3 were associated with T-cell acute lymphoblastic leukemia, in line with previous reports." (PMID 38769532, 2024). "TLX3 encodes a homeobox transcription factor that is known as a master regulator of T cell acute lymphoblastic leukemia." (PMID 35008420, 2022). "TLX3 has also been implicated in disease states in humans, such as in T-cell acute lymphoblastic leukemia or T-ALL." (PMID 25428367, 2014). "Notably, we have reaffirmed the well-established associations between transcription factors TLX1 and TLX3 with T-cell acute lymphoblastic leukemia, as well as HOXA11, PREX2, and RET with AML." (PMID 38769532, 2024). "Although analysis of TLX1/TLX3-induced T-cell acute lymphoblastic leukemia suggests AML1 is an oncosuppressor, overexpression of wt.AML1 promotes the development of mouse T-cell lymphoma and accelerates leukemogenesis in BXH2 mice." (PMID 24098673, 2013). "Another group of T-cell acute lymphoblastic leukemia (T-ALL)-associated oncogenes are homeobox genes and includes members of the NK-like family, TLX1/HOX11, TLX3/HOX11L2 and NKX2-5/CSX, and of the clustered homeobox genes, HOXA5, HOXA9, HOXA10 and HOXA11." (PMID 20565746, 2010). "Three members of the NK-like subfamily of homeobox genes (NKLs), TLX1, TLX3 and NKX2-5, are implicated in T-cell acute lymphoblastic leukemia (T-ALL)." (PMID 19835636, 2009). "T cell acute lymphoblastic leukemia (T-ALL) is a cancer of early thymocytes and is characterized by recurrent chromosomal rearrangements that activate oncogenic transcription factors such as TAL1/2, LMO1/2/3, NKX2.1/2.2, TLX1, TLX3, or HOXA." (PMID 35536646, 2022). "T-cell acute lymphoblastic leukemia (T-ALL) cells represent developmentally arrested T-cell progenitors, subsets of which aberrantly express homeobox genes of the NKL subclass, including TLX1, TLX3, NKX2-1, NKX2-5, NKX3-1 and MSX1." (PMID 28151996, 2017).
leukemia (8 papers, 2016 to 2025). A malignant (clonal) hematologic disorder, involving hematopoietic stem cells and characterized by the presence of primitive or atypical myeloid or lymphoid cells in the bone marrow and the blood. "Similar to the age estimate, our ML–EA program was most enriched among T-ALL derived early in T cell development, namely leukemias with HOXA and TLX3 genetic mutations." (PMID 38867059, 2024). "Indeed, ectopic expression of TLX3 in PHF6-deleted mice facilitated early onset leukemia and a hTLX1;PHF6+/- zebrafish model demonstrated fully penetrant early-onset leukemia development, underscoring the role of cooperation between these mutations in leukemogenesis." (PMID 34381727, 2021). "Again, we observed a remarkable dichotomy in age estimates among the HOXA and TLX3 subtypes versus the TAL1 subtypes, revealing leukemias derived from early developmental stages to have age estimates ranging from ~100–200 years old." (PMID 38867059, 2024). "Conversely, the PLXND1, PLCB4, HOXA9, HOXA10, TLX3, and NKX2‐1 genes had higher expression in the CIMP+ subgroup, compared to the normal T cells and CIMP− leukemias." (PMID 30575306, 2019). "Importantly, some of these genes have already been reported in relation to CML (e.g., AURKB, AZU1, HLA-B, HLA-DMB, PF4) and others have been found to play important roles in different leukemias (e.g., CDCA3, RPL18A, PRG3, TLX3)." (PMID 35008420, 2022).
acute myeloid leukemia (2 papers, 2014 to 2022). Acute myeloid leukemia (AML) is a group of neoplasms arising from precursor cells committed to the myeloid cell-line differentiation. "Further, an in-depth literature analysis revealed that several of these genes play important roles in cancer (CDCA3, ECEL1, EN1, HLA-DMB, SPRR2A, TMEM40) including acute myeloid leukemia (CDCA3, HLA-DMB, RPL18A, PF4, PRG3) and T cell acute lymphoblastic leukemia (TLX3)." (PMID 35008420, 2022).
bladder cancer (2 papers, 2013 to 2023). "In contrast, the loss of TLX3 expression resulted in cisplatin resistance in bladder cancer." (PMID 37627900, 2023). "Bladder cancer patients with TLX3 hypermethylation had higher succinate dehydrogenase (SD) activity (decreased chemosensitivity to cisplatin)." (PMID 37627900, 2023). "Hence, TLX3 methylation can be utilized as a predictive biomarker for cisplatin resistance in bladder cancer." (PMID 37627900, 2023). "As for detected genes, TLX3 (HOX11L2) is a transcription factor highly expressed in T-cell leukemia, and its aberrant methylation was observed in cisplatin-resistant bladder cancer." (PMID 24367375, 2013).
T-cell leukemia (2 papers, 2013 to 2020). A malignant disease of the T-lymphocytes in the bone marrow, thymus, and/or blood. "TLX3 (Hox11) was identified as a transcription factor and a proto-oncogene with an important role in T cell leukemia." (PMID 32318567, 2020).
viral infection (2 papers, 2019 to 2021). "To restrict the viral infection to a particular cell population, we again used Tlx3-Cre mice, a layer 5-specific Cre-line; we injected Cre-dependent AAV expressing oTVB-H-tagBFP (AAV2/9-CAG-DIO-oTVB-H-tagBFP) to the V1 of Tlx3-Cre mice." (PMID 31998081, 2019). "The results of this study also suggested that Nramp and PAI regulated by LncRNA could facilitate virus infection and proliferation for infected cells respectively, while T cell leukemia homeobox 3 (TLX3), as well as galectin 3 function by lncRNA, may play a role in the resistance mechanism." (PMID 34290708, 2021).
Dry skin (1 paper, 2017). Skin characterized by the lack of natural or normal moisture. "Using the mice with CKO of Tlx3 in DRG, we demonstrate here that Tlx3 was indeed required for the expression of a majority of known itch-related receptors and neurotransmitters; consequently, Tlx3cko mice exhibited markedly attenuated acute and dry skin-induced chronic itch." (PMID 28701920, 2017). "Unlike in the dry skin model, the numbers of spontaneous scratch bouts were comparable between Tlx3cko and control mice in the ACD model, demonstrating that down-regulation of Tlx3-dependent pruritic molecules was insufficient to disturb ACD-induced chronic itch." (PMID 28701920, 2017).
glioma (1 paper, 2020). A benign or malignant brain and spinal cord tumor that arises from glial cells (astrocytes, oligodendrocytes, ependymal cells). "In a systematic study on the whole-genome wide glioma methylation status, TLX3 has been shown with specific methylation status in level II and III gliomas." (PMID 33329750, 2020).
itch (1 paper, 2017). "To explore whether the deficits of these Tlx3-dependent molecules affected itch-related behaviors, we examined the acute and chronic itch responses in Tlx3cko and control mice." (PMID 28701920, 2017). "Some of these molecules are also implicated in sensing itch, thus we speculated that Tlx3 in DRG might also mediate the development of pruriceptors and affect itch-related behaviors." (PMID 28701920, 2017).
lung carcinoma (1 paper, 2014). "Breast and lung cancer have many common prognostic signatures, such as hypermethylation of BRCA1, SOX17, and TLX3." (PMID 24842468, 2014).
meningioma (1 paper, 2013). A generally slow growing tumor attached to the dura mater. "For the malignant meningiomas in our study, 26 genes were identified as significantly hypermethylated at promoter CpG islands, including eight genes involved in the biological pathway of neurogenesis (BARHL2, TLX3, FOXR1, HOXA11, HOXA6, HOXA9, OTX2 and PAX3)." (PMID 23349797, 2013).
papillary thyroid cancer (1 paper, 2018). "Kikuchi et al26 identified multiple genes (HIST1H3J, POU4F2, SHOX2, PHKG2, TLX3 and HOXA7) with frequent epigenetic hypermethylation in papillary thyroid cancer, which might function as potential biomarkers." (PMID 30039914, 2018).
penile tumors (1 paper, 2022). "We also described, for the first time, UTRs variants (KDR, CARD11, CSMD3, and TLX3), impacting the miRNAs’ binding sites in penile tumors." (PMID 35884575, 2022).
cancer (10 papers, 2013 to 2022). A tumor composed of atypical neoplastic, often pleomorphic cells that invade other tissues. "As a result, 14 genes were found to be regulated by miRNAs (miRabel score ≤ 0.05), four of which are cancer-associated genes (CARD11, CSMD3, KDR, and TLX3)." (PMID 35884575, 2022). "Herein, we found 14 genes with UTR variants, of which four cancer-associated genes harbor variants in 3′ UTR (KDR and CARD11) and 5′ UTR (CSMD3 and TLX3)." (PMID 35884575, 2022). "There are no integration sites in chromosomes 21, 22, and X. Only five genes of the many associated with MCPyV integration, namely SF3B1, TLX3, CD74, MYC, and KMT2D, are cancer-linked genes listed in the COSMIC database." (PMID 32878339, 2020). "We observed similar cancer-specific H3K4me3-BDs associated with hijacking of super-enhancers of other common oncogenes in B cell (MAF, MYC, and FGFR3/NSD2) and T cell malignancies (LMO2, TLX3, and TAL1)." (PMID 34933939, 2022). "This indicates that TLX3 expression was suppressed during hepatitis B virus-related cancer." (PMID 34290708, 2021). "Additionally, four cancer-associated genes (CARD11, CSMD3, KDR, and TLX3) carried untranslated regions (UTRs) variants, which may impact gene regulation by affecting the miRNAs hybridization regions." (PMID 35884575, 2022). "A similar fraction of cancer samples showed high methylation in each gene (2/20 for HIST1H3J, 8/20 for POU4F2, 4/20 for SHOX2, 5/20 for PHKG2, 6/20 for TLX3, and 4/20 for HOXA7)." (PMID 24367375, 2013).
tumour (5 papers, 2014 to 2023). "It has been reported that Phf6 loss could significantly accelerate T-ALL development driven by co-mutation with JAK3M511I or with aberrant expression of TLX3, suggesting PHF6 as a tumor suppressor in T-ALL." (PMID 37393343, 2023). "Interestingly, PHF6 mutations are associated with tumours expressing the TLX1 and TLX3 oncogenes." (PMID 26103525, 2015). "A systems biology analysis of the regulatory circuit controlled by TLX1 and TLX3 in T-ALL found these factors as master regulators and identified the runt-related TF 1 (RUNX1) as a tumor suppressor." (PMID 25428367, 2014).
neurodevelopmental disorder (1 paper, 2016). A behavioral and cognitive disorder with onset during the developmental period that involves impaired or aberrant development of intellectual, motor, or social functions. "We assume that Tlx3 may be a part of this complex gene regulatory network that is disrupted in neurodevelopmental disorders such as ASD which definitely needs to be investigated further." (PMID 27452274, 2016).
TLX3 also shares sentences with these, for which no sentence is quoted: acute lymphoblastic leukemia (10 papers); chronic myeloid leukemia (1); glioblastoma (1); hematological malignancies (1); infection (1); pancreatic cancer (1); T-cell lymphoma (1).